CST7 (cystatin F)
Diseases named in the same sentence as CST7 in open-access papers (continued):
Sharing a sentence is not in itself a finding about the gene and the disease.
tumor (25 papers, 2017 to 2026). "Selected genes, relevant to cytotoxic immune cells, microglia/macrophages, and tumor-associated genes, were clustered based on the correlation strength with CST7 into three clusters." (PMID 41229419, 2025). "We identified a dataset (GSE101584) for tumor-associated neutrophils in a mouse cancer model and found a significant increase in CST7 expression compared to that in naïve neutrophils." (PMID 33868254, 2021). "MG from tumor bearing animals show also upregulation of Timp2, Serpine2, Cst7, and Ctsd, genes encoding proteases or their modulators participating in reorganization of extracellular matrix, which may reflect invasion supporting properties." (PMID 33608526, 2021). "In this research, our objective was to examine the CST7 and has-miR-4793-5p gene expression in BC tumor tissues and adjacent normal tissues." (PMID 39552709, 2024). "By inhibiting cathepsins C and H, cystatin F prevents the activation of granzymes and perforin and thus decreases anti-tumor immune responses." (PMID 38092995, 2023). "Because cystatin F can act in trans, its expression by other immune cells in the tumor microenvironment or tumor cells can decrease the cytotoxic potential of NK cells as well." (PMID 38092995, 2023). "To conclude, our results suggest that cystatin F is an important molecular mediator in tumour microenvironments and is responsible for shaping the anti-tumour immune response and function of cytotoxic lymphocytes." (PMID 33291222, 2020). "A strong correlation with CST7 is maintained after adjusting for tumor purity (PDCD1, TIGIT)." (PMID 41229419, 2025). "Alternatively, other post-transcriptional modifications in tumor cells could affect CST7 mRNA levels, despite higher protein content." (PMID 41229419, 2025). "Compared to Mo detected in normal brains, Mo detected in PDOXs showed higher expression levels of genes associated with pro-tumorigenic TAMs (e.g., Cxcl13, Ctsd, Ccl4, Apoe) as well as Mg mimicry (e.g., Spp1, Trem2, Cst7, Tyrobp), further confirming an active crosstalk with tumor cells." (PMID 38566128, 2024). "CD8+ TEXs expressing CST7 instead of CTLA4 or PDCD1 was detected in tumour tissues." (PMID 36855810, 2023). "Cystatin F is secreted into the tumor microenvironment by tumor and other immune cells." (PMID 36147668, 2022). "Given that cystatin F also inhibits cathepsin C in mice, this supports the hypothesis that cystatin F plays a role in the tumor microenvironment." (PMID 33868254, 2021). "Tumour cells could also internalise cystatin F present in tumour microenvironments into which it could be secreted by several other cell types, especially immune cells such as dendritic cells, monocytes or even cytotoxic lymphocytes." (PMID 33291222, 2020). "A protective role of cystatin F in target cells might be especially important in tumour microenvironments in which cystatin F could be exploited by tumour cells to evade the anti-tumour immune response." (PMID 33291222, 2020). "However, further studies of the effects of rLm-cystatin F on tumor cells are still required in the near future." (PMID 30501116, 2018). "Within the tumor microenvironment besides tumor cells several other cell types, including immune cells could be a source of increased level of cystatin F." (PMID 29180998, 2017). "Since this inhibitor can be produced and secreted by tumor cells, we investigated whether extracellular cystatin F can reduce the cytotoxicity of NK cells." (PMID 29180998, 2017). "In contrast to the majority of other type II cystatins which are generally downregulated in tumors, cystatin F was found to be markedly upregulated in tumors of colorectal cancer patients compared to the corresponding non-tumor tissue, correlating with higher frequency of liver metastasis." (PMID 29180998, 2017).
tumor (continued). "Therefore, the presence of the high-mannose glycosylated cystatin F in tumor microenvironment could be detrimental to the anti-tumor immune response, as this type of cystatin F can be internalized into cytotoxic immune cells decreasing their cytotoxicity." (PMID 38092995, 2023). "Modulating the glycosylation of endogenous cystatin F in NK cells could increase their anti-tumor function, while inhibiting the internalization of extracellular cystatin F via M6P could prevent its in trans action and the effect of the tumor microenvironment on NK cell cytotoxicity." (PMID 38092995, 2023). "Furthermore, if cystatin F is secreted by neutrophils in a tumor microenvironment, then it may contribute to pro-tumor immunosuppression." (PMID 33868254, 2021). "Indeed, intracellular cystatin F acts as an upstream regulator of split anergy in NK cells, a functional phenotype that appears after the interaction of NK cells with tumour cells or monocytes and is characterised by decreased cytotoxicity and increased cytokine secretion." (PMID 33291222, 2020). "Moreover, extracellular cystatin F present in the tumour microenvironment may attenuate granzyme A and B activity and decrease recipient NK cell cytotoxicity." (PMID 33291222, 2020). "In addition, previous studies have shown that angiogenesis is closely related to tumor progression as novel blood vessels would provide nutrition for the tumor cells, thus, rLm-cystatin F might also affect the activity of tumors." (PMID 30501116, 2018). "In the postinfusion NK cells, NK1 was the dominant subcluster, expressing high levels of cytotoxic effector genes (CST7, SRGN, and GZMA), indicating its key role in tumor cell killing." (PMID 40315330, 2025). "We have previously shown that cystatin F is expressed on the protein level in GBM tissue in various cell types, besides microglia/macrophages, also in tumor stem cells and differentiated tumor cells." (PMID 41229419, 2025). "Subsequently, we analyzed DEGs between tumor and normal tissues and selected the top five DEGs with the highest expression, which were SPP1, AKR1C2, AKR1B10, AGT, and EPHX1 in tumor tissues and NKG7, KLRD1, KLRB1, CCL5, and CST7 in normal tissues." (PMID 35967424, 2022). "Conversely, there was no significant differentiation in the expression of CST7 and hsa-miR-4793-5p in different age, metastasis, and tumor type (lobular or Ductal) groups." (PMID 39552709, 2024). "Tumor-specific IL-7Rhi CD8+ T cells (cluster 4) expressed intrinsic cytotoxic mediators including natural killer cell granule protein 7 (Nkg7), killer cell lectin receptor D1 (Klrd1), cathepsin W (Ctsw), cystatin F (Cst7), and Ccl5, suggesting a capacity for cytotoxicity." (PMID 37459511, 2023).
cancer (15 papers, 2010 to 2025). A tumor composed of atypical neoplastic, often pleomorphic cells that invade other tissues. "The involvement of CST7 in cancer is intricate and potentially particular to certain types of cancer, as indicated by recent studies conducted on different types of cancer." (PMID 39552709, 2024). "The disparity underscores the potential context-specific functions of CST7 in various forms of cancer and underscores the necessity for cancer-specific research." (PMID 39552709, 2024). "Cystatin F is more commonly known for its use by cancer cells to immunosuppress granule-mediated cytotoxicity of effector CD8 + T cells and NK cells." (PMID 38879499, 2024). "The expression patterns of 3 key genes were different in the pseudo-trajectories of the 3 types of cells, but IL1B and ITGA5 were more similar, suggesting that CST7 and the other two work in a different mode of action in cancer." (PMID 36969161, 2023). "Taking into account that we used cancer cell lines to examine cystatin F glycosylation in this study, we demonstrated similar cystatin F glycosylation profiles between NK-92 and primary NK cells and between TALL-104 and CD8 + T cells." (PMID 38092995, 2023). "Overall, our results indicate that cystatin F is an important mediator that can impair the killing efficiency of cytotoxic T lymphocytes and thus suggest that it is a possible target for cancer immunotherapy." (PMID 33291222, 2020). "This could involve designing experiments to manipulate the levels of miR-4793-5p and CST7 and observing the corresponding changes in cancer cell behavior, such as proliferation, invasion, and metastasis." (PMID 39552709, 2024). "By manipulating the glycosylation machinery, we could redirect cystatin F trafficking and improve the cytotoxic potential of NK cells for cancer immunotherapy." (PMID 38092995, 2023). "However, the expression of CST7 has been detected in various human cancer cell lines established from malignant tumours." (PMID 35865633, 2022). "The regulatory ability of in trans cystatin F could be exploited by cancer cells that, together with cancer stem cells and monocytes, overproduce and secrete cystatin F, in order to lower the antitumor immune cell cytotoxicity." (PMID 31555270, 2019). "Furthermore, extending the investigation to assess the expression of miR-4793-5p and CST7 in other cancer types may uncover broader implications for their roles in cancer biology." (PMID 39552709, 2024). "Additionally, studies have suggested its potential role in cancer progression, indicating that inhibiting CST7 activity could be a viable strategy for cancer treatment." (PMID 39552709, 2024). "Prevention of cell internalization or monomerization of cystatin F by modifying the glycosylation profile or by targeting the peptidase responsible for cystatin F activation could greatly increase the cytotoxic potential of NK cells and improve the existing immunotherapies for cancer patients." (PMID 29180998, 2017). "Hypomethylation or gain of CST7 has not been reported in OSCC but has been proposed as a prognostic biomarker for other carcinomas." (PMID 37245006, 2023).
infection (9 papers, 2021 to 2025). The state of being infected such as from the introduction of a foreign agent such as serum, vaccine, antigenic substance or organism. "Compared to control mice, JHMV infection of Cst7-/- mice resulted in an increase in spinal cord demyelination at days 14 (p < 0.05) and 21 (p < 0.001)." (PMID 38879499, 2024). "This includes the upregulation of gene programmes involved in other neurodegenerative disorders, such as Apoe, Aif1, Cst7, Itgax, Tyrobp, and Trem2 at the point of infection in which clinical symptoms are detected." (PMID 36180478, 2022). "CST7 was increased during infection with influenza A virus (IAV), respiratory syntactical virus (RSV) and human immunodeficiency virus (HIV) infection (effect size = 1.47, 1.18, 1.54 respectively)." (PMID 33868254, 2021). "By targeting cystatin F expression, the levels of proteolytic activity could be restored to the basal levels detected before infection." (PMID 37513033, 2023). "MA10 infection induced six down-regulated (Pllp, Malat1, Myrf, Mag, Ptgds, Ugt8a) and two upregulated DEGs (Sgk1, Mbp), while Aβ pathology resulted in one down-regulated (Hmgb1) and ten up-regulated DEGs (Apoe, B2m, Clu, Cstd, Gfap, Psen1, Pllp, Cst7, Cd9, Plp1)." (PMID 41497643, 2025). "Moreover, Isg12+Cst7+ neutrophils expressed Cd274 and Il10rb, potentially interacted with activated cytotoxic T cells and Slamf9+ macrophages, and jointly established the favoring niches for the resolution of inflammation at the late stage of infection." (PMID 39414783, 2024). "Myeloid dendritic cells in dormant infections also showed notable differences in mRNA expression, affecting neutrophil recruitment (C1QA, C1QB, ITGAM), immune checkpoint regulation (IFITM2, IFITM3, CST7, THBS1), and T-cell response (VISIG4, V-set immunoglobulin domain containing 4)." (PMID 39563367, 2024).
neurodegenerative disease (7 papers, 2011 to 2023). A disorder of the central nervous system characterized by gradual and progressive loss of neural tissue and neurologic function. "Interestingly, we also detected reductions in disease-associated microglia (DAM)/microglial neurodegenerative disease (MGnD) genes such as Cst7, Clec7a, and Spp1, suggesting that microglia adopted a dampened DAM/MGnD state despite no changes in IBA1+ microglia staining." (PMID 36922879, 2023). "Some studies have suggested CF may play a protective role in a demyelination model by inhibiting cathepsin C or negatively regulating microglial phagocytosis but the possible disease-modifying role of Cst7/CF in amyloid-driven neurodegenerative disease is unknown." (PMID 38085657, 2023). "Upregulated genes in DAM, also known as Aβ-plaque-associated microglia, include Axl, Apoe, Clec7a, Itgax, Galectin 3 (LGALS3), and cystatin F (CST7), which are considered to be involved in neurodegenerative diseases." (PMID 36209099, 2022). "However, despite such striking and robust upregulation, the function of Cst7 in neurodegenerative disease is not understood." (PMID 38085657, 2023). "The upregulation of Cst7 in the present BSE model, described in other TSE, can be a consequence of the induction of lysosomal proteases or could have a compensatory role against the accumulation of abnormal protein in some neurodegenerative diseases." (PMID 22035425, 2011).
neurologic disease (2 papers, 2022 to 2024). "DAM genes Clec7a, Itgax and Cst7 are associated with innate immune responses in the setting of neurological diseases." (PMID 36419137, 2022). "We used cystatin F null-mutant mice (Cst7-/-) with a well-established model of murine coronavirus-induced neurologic disease to evaluate the contributions of cystatin F in host defense, demyelination and remyelination." (PMID 38879499, 2024).
bacterial infection (1 paper, 2023). "This is the first report connecting cystatin F and a bacterial infection in macrophages." (PMID 37513033, 2023).
central nervous system diseases (1 paper, 2012). "Recent studies have shown that cystatin F, a potent endogenous cysteine protease inhibitor, is primarily expressed in activated microglia in central nervous system diseases but is not expressed in the normal brain." (PMID 23285090, 2012).
vasculopathy (1 paper, 2022). "In addition, our results revealed the microvascular profile that favors the disease phenotype of microglial mirrored in the upregulation of TYROBP, TREM2, and Cst7 in both early and late stages of CAA vasculopathy." (PMID 35813502, 2022).
CST7 also shares sentences with these, for which no sentence is quoted: dementia (2 papers); pancreatic ductal adenocarcinoma (2); bacterial meningitis (1); bacterial sepsis (1); brucellosis (1); cannabis dependence (1); dengue (1); Encephalopathy (1); experimental autoimmune encephalomyelitis (1); Graves disease (1); immune disorders (1); influenza (1); ischemic stroke (1); Krabbe disease (1); metastatic cancers (1); metastatic melanoma (1); myeloid leukaemia (1); nicotine dependence (1); osteoporosis (1); ovarian carcinoma (1); Parkinson disease (1); protein-misfolding diseases (1); systemic onset idiopathic juvenile arthritis (1).